ENSG00000252138
Synonyms: LOC124900381
Gene: Small nucleolar RNA gene on chromosome 16 (7,726,841 to 7,726,951, reverse strand). Ensembl gene ENSG00000252138.
Gene Ontology:
Biological process: RNA processing
Cellular component: nucleolus
Homologues: Paralogues in human: SNORA40B (84% identical), SNORA40 (83% identical), SNORA40C (78% identical).